APOE (apolipoprotein E)
Diseases named in the same sentence as APOE in open-access papers (continued):
Sharing a sentence is not in itself a finding about the gene and the disease.
atherosclerosis (continued). "In addition, in an ovariectomized ApoE -/- mice model, it was demonstrated that ESRα inhibited the synthesis and secretion of proprotein convertase subtilisin/kexin type 9 (PCSK9) and subsequently lowered the accumulation of cholesterol and triglyceride to prevent post-menopausal atherosclerosis." (PMID 36833280, 2023). "The absence of CD4+ T cells in apoE‐knockout mice could ameliorate atherosclerosis." (PMID 36988256, 2023). "However, hepcidin/Fpn1 axis may not play a major role in atherosclerosis progression in ApoE–/– mice." (PMID 35669479, 2022). "Studies conducted with human APOE gene replacement mice, in which the endogenous mouse ApoE gene has been replaced by the human APOE2, APOE3, or APOE4 gene, provided additional insights toward understanding how the various major apoE isoforms may influence lipid metabolism and atherosclerosis." (PMID 36077289, 2022). "Experiments in ApoE-KO mice lacking the antioxidant system also found that the development of atherosclerosis and the increase of mitochondrial ROS both occurred, suggesting that the increase of ROS caused by mitochondrial dysfunction may play a role in atherosclerosis." (PMID 35047104, 2022). "This discrepancy suggests that pathophysiological redox changes in the serum apoE-Cys-thiol by or for the development of atherosclerosis accompanied by dyslipidemia would be quite different from those by or for the development of dyslipidemia without atherosclerosis." (PMID 34286848, 2021). "Unlike individuals with APOE Ɛ2, individuals with APOE Ɛ4 have lower plasma concentration of APOE and C-reactive protein (CRP), along with higher plasma levels of cholesterol, LDL-C, APOB, lipoprotein (a), atherosclerosis, and BMI, and are at a higher risk of CVD." (PMID 34172062, 2021). "Considering that the exact role of Pim-2 in atherosclerosis remains unknown, we investigated whether Pim-2 kinase inhibits atherosclerotic inflammation by suppressing the mTORC1 pathway in ox-LDL-treated THP-1-derived macrophages and ApoE -/- mice fed a high-fat diet." (PMID 34547720, 2021). "By using PMs and BMDMs isolated from ApoE knockout mice which were utilized as a classical in vitro model for atherosclerosis, we aimed to investigate the potential role of PAK1 in macrophage activation that may contribute to the development of atherosclerosis." (PMID 34603600, 2021). "While Western diet or ApoE knockout mouse models do not result in formation of progressive atherosclerotic lesions, these models nevertheless provide important insights into its early development and first-wave responses of ECs and SMCs to atherosclerosis development." (PMID 32630148, 2020). "Using ApoE(–/–) mouse model, it was shown that over-expression of SAA3 results in a 4-fold increase in atherosclerosis lesion size over control while knockdown of SAA3 decreases atherosclerosis, implying that this gene may be a new therapeutic target for atherosclerosis." (PMID 33644114, 2020). "Indeed, DC depletion in hyperlipidemic CD11c-DTR ApoE−/− mice leads to increased hypercholesterolemia but no change in atherosclerosis due to lower DC-driven T-cell activation, suggesting that there is a close relationship between DCs and cholesterol homeostasis." (PMID 39649554, 2020).
atherosclerosis (continued). "We suggest that female APoE KO rats were not affected by diving but this is not surprising; previous studies have shown that endothelium-dependent relaxation is more severely impaired in atherosclerosis arteries of males compared to females, both in humans and animals." (PMID 31695628, 2019). "The trans-genetic overexpression of PAPP-A in vascular smooth muscle cells (VSMCs) of ApoE KO mice directly resulted in accelerated expansion of the atherosclerotic lesion area and PAPP-A KO mice could resist VSMCs proliferation and migration—a sign of advanced atherosclerosis." (PMID 30302668, 2019). "Moreover, consistent with a proatherosclerotic role for PCKS9 independent of lipid levels, PCKS9 overexpression accelerated atherosclerosis in apoE-knockout mice without significantly affecting plasma lipid levels, while gene inactivation significantly reduced it." (PMID 30558209, 2018). "Importantly, lack of TSP-1 protected ApoE−/− mice against hyperglycemia-induced atherosclerosis." (PMID 28345659, 2017). "Moreover, double-knockout mice, lacking PTX3 and apolipoprotein E, exhibit increased atherosclerosis and macrophage accumulation in atherosclerotic lesions compared with that observed in apolipoprotein E only knockout mice, suggesting that PTX3 possesses a cardiovascular protective function." (PMID 28955836, 2016). "Thus, in atherosclerosis prone ApoE−/− rats, RDN failed to improve overall inflammatory activation, triggered by hypercholesterolemia, but influenced activation of MNCs, while circulating interleukin levels and local aortic inflammatory activation was not modulated." (PMID 27277003, 2016). "In addition, we found that xyloketal B could improve the lipid metabolism disorder in atherosclerosis, although it did not affect the body weight of apoE−/− mice fed with high-fat diet." (PMID 25874925, 2015). "The increased testosterone levels are unlikely to contribute to the increased atherosclerosis in the ARKO females; testosterone should have mainly estrogenic effects in the absence of the AR, and exogenous testosterone reduces atherosclerosis in apoE-deficient females." (PMID 25550469, 2015). "Complicating this issue, while atherosclerosis in the aorta of PAI-1−/−/ApoE−/− and PAI-1+/+/ApoE−/− were similar, there was a decrease in disease progression at the carotid bifurcation in PAI-1−/−/ApoE−/− suggesting PAI-1 may potentiate lesion development at sites of turbulent flow." (PMID 26110015, 2014). "Interestingly, we previously found that in apolipoprotein E knockout mice (a widely used atherosclerotic mouse model), the expression levels and the circadian rhythms of clock genes changed compared to C57BL/6 J mice, and these changes were accompanied with a progression of atherosclerosis." (PMID 24418196, 2014). "The knockout of IKKε prevented significant atherosclerosis lesions in the mouse aorta from in both wild-type and ApoE knockout mice fed a HFD, suggesting that IKKε may play a vital role in HFD-induced atherosclerosis and would be an important target for the treatment of atherosclerosis." (PMID 23741427, 2013). "We also found certain HS disaccharides (D0H0) associated with APP and other proteins increased in CAA (OLFML3, FRZB, ApoE, FGA), as well as with ApoE genotype, but not with atherosclerosis." (PMID 40156913, 2025).
atherosclerosis (continued). "Mice do not usually develop atherosclerosis, due to the high protective HDL-C in their plasma, therefore, by knocking out ApoE and feeding the mice on a high fat diet for 4 weeks, we assessed the earliest possible changes in the vasculatures." (PMID 37539090, 2023). "Although we assume that suppression of atherogenesis by VE‐PTP deletion is not specific to ApoE−/− mice, other models should be examined to develop a more complete understanding of the potential of VE‐PTP as a therapeutic target in atherosclerosis." (PMID 36740996, 2023). "The wall thicknesses in atherosclerotic vessels were not altered between genotypes, while the IMR was significantly enhanced in ApoE−/−/CRP4+/+ aorta, confirming favourable effects on the extent of atherosclerosis when CRP4 is lacking as observed in dKO." (PMID 35456043, 2022). "As mice do not develop atherosclerosis spontaneously, genetic manipulation is necessary for atherogenesis, including genetic deletions of either LDL-R or ApoE." (PMID 36290415, 2022). "In ApoE-/- mice, lacking MHC II, which is required to activate Th0 cells, are characterized by decreased severity of atherosclerosis." (PMID 36685487, 2022). "These pathways and key metabolic steps in RCT to protect against atherosclerosis, are not observed for HDL without apoE." (PMID 35371605, 2022). "Genetic manipulation by knocking out ApoE gene in mice results in spontaneous development of hypercholesterolemia (dominated by non-HDL-C) and atherosclerosis." (PMID 33413490, 2021). "A single intravenous injection of the PCSK9 mAb, alirocumab, in hyperlipidemic APOE*3Leiden.CETP transgenic mice, decreased non-HDL-C, inflammatory parameters, and atherosclerosis lesion size and improved plaque stability in a dose-dependent manner." (PMID 33440821, 2021). "Aortas from these mice, when transplanted into apolipoprotein E (ApoE)−/− mice fed a high-fat diet, fail to express CCL2 and MIF and do not develop atherosclerosis, in contrast to the florid lesions seen in control WT aortas." (PMID 33458623, 2021). "When ApoE−/− mice were reconstituted with bone marrow from various human APOE gene replacement mice, effective reduction of atherosclerosis was observed with marrow cells obtained from APOE3 but not APOE2 and APOE4 gene replacement mice." (PMID 34425108, 2021). "Another limitation to be considered with ApoE−/− mice is the high levels of VLDL particles, which is not typical in human atherosclerosis." (PMID 33258000, 2020). "PECAM-1 is also an important factor in atherosclerosis, as a lack of PECAM-1 in ApoE−/− mice will significantly reduce the lesion size of the aortic arch and aortic sinus." (PMID 33371312, 2020).
atherosclerosis (continued). "To conclude, we demonstrate that constant light increases plasma cholesterol while decreasing circulating leukocytes in female APOE*3-Leiden.CETP mice, resulting in no net effect on atherosclerosis." (PMID 32915671, 2020). "For the murine model of atherosclerosis, we found no any difference in the serum lipid profiles between FBXW2 (P3) and control‐treated ApoE−/− mice." (PMID 33101872, 2020). "Accordingly, ApoE−/− mice, but not wild-type mice, were used in this study to investigate the effect of vanadium derivatives, including NaVO3 and VOSO4, on atherosclerosis." (PMID 31817202, 2019). "Transgenic APOE−/− mice overexpressing APP show atherosclerotic lesions of increased size and with enhanced inflammation in comparison with APOE−/− mice, while APOE−/− mice lacking APP have less atherosclerosis than APOE−/− mice." (PMID 30893771, 2019). "MiR-155 and miR-221 were the only miRNAs modulated in all four HRDs; and miR-155 deletion in our ApoE-/- mice led to a new MHO model, whereby obesity, NAFLD, and hyperinsulinemia without insulin resistance were present along with reduced atherosclerosis." (PMID 30369883, 2018). "To evaluate the role of GTPCH1 in the development of atherosclerosis, we used lentivirus overexpression of GPF or GTPCH1 with LV.GFP or LV.GTPCH1 in ApoE−/− mice fed an HFD with or without nicotine." (PMID 30091833, 2018). "Seven days after the initiation of luseogliflozin administration, atherosclerosis-related mRNA levels in the aorta were compared among four groups; i.e., wild type C57/BL6J, native ApoE KO, and NA/STZ-treated ApoE KO mice, with or without luseogliflozin." (PMID 28777298, 2017). "Therefore, atherosclerosis in ApoE knockout model may be independent of plasma lipid levels." (PMID 28095860, 2017). "In ApoE−/− mice, the absence of CD36 protects them from the development of atherosclerosis and lesion complexity." (PMID 28084332, 2017). "Since only 2% of CBS-/-ApoE-/- mice survived up to 6 months of age, the pathophysiological relevance of CBS-/- to H2S metabolism in atherosclerosis is not clear." (PMID 29018349, 2017). "Although no changes in the plasma lipids between ApoE−/− and ApoE−/−Adamts4−/− mice were observed, removal of ADAMTS4 attenuates atherosclerosis." (PMID 27491335, 2016). "For instance, we reported that ApoE null mice exposed to ambient UFP for 5 weeks, exhibited proinflammatory HDL and enhanced atherosclerosis, at the same time when there were no significant changes in plasma levels of IL-6 and IL-8 (unpublished)." (PMID 27221567, 2016). "Indeed, in the absence of atherosclerosis and macrophage accumulation, VDR ablation was still associated with an increased arterial expression of adhesion molecules implying that the enhanced plaque formation in apoE-/-VDR-/- mice was due to a strong proinflammatory milieu fostered by VDR deletion." (PMID 26322890, 2015). "To study the functional role of VDR in atherosclerosis, we generated animals lacking both VDR (VDR-/-) and apoE (apoE-/-) gene." (PMID 26322890, 2015). "Consequently, the ApoE−/− mouse model may not be ideal for studies of human CRP in atherosclerosis." (PMID 24872599, 2014). "In spite of the fact that aortic MCP1 mRNA expression significantly correlated with the degree of atherosclerosis, there was no further induction under L-NAME treatment in the ApoE-null mice." (PMID 24587793, 2014). "Here we have used apoE−/−/COX-2−/− mice to show that, whilst COX-2 profoundly limits atherosclerosis, this protection is independent of local prostacyclin release." (PMID 24887395, 2014).
atherosclerosis (continued). "When crossed with ApoE null mice and fed a Western diet, mice lacking SGEF showed a significant decrease in the formation of atherosclerosis in multiple aortic areas." (PMID 23372835, 2013). "An ex vivo application of MT spin-echo at 11.7T to ApoE-/- mice that identified the difference in MTC between fibrous tissue and lipid core showed that MT was relevant to non-human models of atherosclerosis." (PMID 22107813, 2011). "Therefore, future studies using appropriate animal models of atherosclerosis, such as low density-lipoprotein-deficient or apolipoprotein E-deficient mice, have to clarify whether or not diets containing high levels of 13-HODE promote atherosclerosis development." (PMID 22129452, 2011). "It was recently reported that atherosclerosis-prone ApoE (−/−) mice simultaneously lacking JNK2 (ApoE (−/−), JNK2 (−/−) mice) developed less atherosclerosis compared to ApoE (−/−) mice." (PMID 20182627, 2010). "Exogenous IFN-γ has been shown to enhance high fat diet induced atherogenesis in ApoE-/- mice and IFN-γ and TNF-α knockout mice did not develop severe atherosclerosis when fed with a diet with high cholesterol." (PMID 19604372, 2009). "However, no reduction in atherosclerosis was observed in the absence of endogenous SAA1.1 and SAA2.1 in apoE-/- (DKO) mice, while suppression of SAA3 in DKO mice significantly reduced atherosclerosis." (PMID 40429677, 2025). "However, COX-2 deletion did not alter vascular prostaglandin production in apoE-/- and healthy mice, suggesting that COX-2 protects against atherosclerosis independently of local vascular prostacyclin." (PMID 34592918, 2021). "However, we reported no reduction in atherosclerosis in the absence of endogenous SAA1.1 and SAA2.1 in apoE−/− (DKO) mice fed with a standard rodent diet or western diet." (PMID 34944527, 2021). "However, in ApoE-/- mice, IgM and IgG1 did not bind to MDA-oxLDL at high levels but bound to numerous self-proteins, presumably increasing inflammation and promoting atherosclerosis consistent with previous studies." (PMID 34305930, 2021). "In our study, we found that long-term CIH exposure aggravated atherosclerosis in ApoE–/– mice fed a high-fat diet, and CIH followed by normoxia exposure significantly reduced atherosclerosis in ApoE–/– mice compared with mice consistently exposed to long-term CIH exposure." (PMID 32328084, 2020). "When crossed with apoE-negative mice, CD36 null mice were resistant to developing atherosclerosis." (PMID 29883404, 2018). "Employing hyperlipidemic ApoE−/− mice and ApoE−/− mice lacking TLR2, it was observed that those lacking TLR2 failed to accelerate atherosclerosis in response to P. gingivalis, supporting that TLR2 is necessary for the infection-accelerated atherosclerosis phenotype." (PMID 29621153, 2018). "Moreover, ApoE−/− mice with a heterozygous deletion of the IR and its downstream target, IR substrate 1 (IRS1), also develop accelerated atherosclerosis, as well as the mice lacking IR substrate 2 (IRS2−/−)." (PMID 28899902, 2017).